POLD4 (DNA polymerase delta 4, accessory subunit)
Diseases named in the same sentence as POLD4 in open-access papers (continued):
Sharing a sentence is not in itself a finding about the gene and the disease.
cancer (10 papers, 2015 to 2024). A tumor composed of atypical neoplastic, often pleomorphic cells that invade other tissues. "POLD4 is associated with cancer progression, while the mechanisms underlying PMT and tumor radiation resistance have remained elusive." (PMID 38829550, 2024). "The findings demonstrated a significant association between elevated POLD4 levels and poorer OS in various cancer types, including LGG, LAML, GBM, LUAD, PAAD, and UVM." (PMID 37762224, 2023). "In this study, an extensive investigation was conducted to examine the differences in POLD4 expression, prognostic significance, and its underlying functions across 33 different types of human cancers." (PMID 37762224, 2023). "The differential expression of POLD4 across various cancer types underscores its potential as a diagnostic and prognostic marker." (PMID 37762224, 2023). "In GBMs, POLD4 is associated with cancer patient resistance to radiotherapy and tumor recurrence." (PMID 38829550, 2024). "The high expression of POLD4 has been shown to enhance DNA replication fidelity, reducing the risk of accumulating mutations that could lead to cancer initiation or progression." (PMID 37762224, 2023). "Specifically, POLD4 exhibited a positive correlation with the infiltration levels of tumor-associated fibroblasts, macrophages, monocytes, and neutrophils across various TCGA cancers." (PMID 37762224, 2023). "However, the cancer driving effect of POLD4 was associated with downregulation of this gene and here we find it consistently amplified." (PMID 25569148, 2015). "However, the associations between POLD4 and some potential tumor-related pathways may provide valuable clues for understanding its unique functional mechanisms in cancer." (PMID 37762224, 2023). "Other significant genes, such as LAT, DLX4 and POLD4, are related to inflammatory/immune processes and various cancer types." (PMID 39020437, 2024). "A recent meta-analysis of TCGA (The Cancer Genome Atlas) data has shown that POLD4 was significantly overexpressed in 17 types of cancer compared to the adjacent normal tissue." (PMID 38790250, 2024). "POLD4 has been observed in the development and progression of multiple cancers, including hepatocellular carcinoma, lung cancer, and cisplatin resistance in gastric cancer." (PMID 38829550, 2024). "We conducted an analysis across various cancer types to evaluate the relationship between POLD4 expression and the characteristics of the tumor microenvironment (TME)." (PMID 37762224, 2023). "Our research highlights the essential role of POLD4 in cancer immunity, where the characteristics of the tumor microenvironment (TME) serve as valuable indicators for evaluating tumor cell responses to immunotherapy and influencing clinical outcomes." (PMID 37762224, 2023). "It was revealed that the POLD4 expression displayed a consistent positive association with the immune score, ESTIMATE score, and stromal score across a majority of the cancer types analyzed." (PMID 37762224, 2023). "Using a blend of R programming and internet resources, we initiated an extensive examination into the correlation between POLD4 expression and the various elements of cancers." (PMID 37762224, 2023). "Our research findings indicate that the expression pattern of POLD4 not only serves as a robust indicator of prognosis in cancer patients but also holds promising potential as a new focus for treatment." (PMID 37762224, 2023). "When we analysed the cancer-specific genes like Cdc20, Hmmr, Tpx2, Cenpf, Birc5, Ube2c, Foxm1,Pold4, Nup210, Cenpm and Orc1, these pro-carcinogenic genes found to be over expressed in the disease control group." (PMID 36650455, 2023). "POLD4’s enrichment in these pathways suggests its involvement in various aspects of cancer progression and immune regulation." (PMID 37762224, 2023).
cancer (continued). "By investigating the ImmuCellAI and TIMER2 databases, we observed the significant impact of POLD4 on immunocyte infiltration in various cancer types, especially in LGG and GBM." (PMID 37762224, 2023). "The exact molecular mechanisms of POLD4 in cancer initiation and progression remain incompletely understood and require further research." (PMID 37762224, 2023). "By integrating the GTEx and TCGA databases, we conducted an analysis to examine the variation in POLD4 expression across 33 distinct cancer types." (PMID 37762224, 2023). "POLD4 stood out due to its intriguing expression patterns, correlation with prognosis, and functional enrichment in multiple cancer types, which piqued our interest." (PMID 37762224, 2023). "Lastly, the extension of our findings to other tumor types is preliminary, and further research is needed to ascertain the broader implications of POLD4 in cancer biology." (PMID 37762224, 2023). "To better understand the connections between POLD4 and cancer immunity, we analyzed the correlations between POLD4 expression and immune cell infiltrations." (PMID 37762224, 2023). "Our research findings indicate that the POLD4 gene is significantly overexpressed in 17 types of cancer compared to adjacent normal tissues." (PMID 37762224, 2023). "By utilizing data from the CTRP dataset, we examined the relationship between POLD4 expression and drug sensitivity or resistance in cancer cells." (PMID 37762224, 2023). "In our discovery, we observed the involvement of POLD4 in numerous pathways that contribute to cancer progression and immune regulation." (PMID 37762224, 2023). "The results demonstrated a positive link between POLD4 expression and mDNAsi score in various cancer types, specifically OV, UVM, THYM, PRAD, and LGG." (PMID 37762224, 2023). "We discovered that POLD4 is upregulated in various malignant tumors, demonstrating a significant correlation with poor patient survival prognosis." (PMID 37762224, 2023). "Despite these studies reporting the role and mechanisms of POLD4 in relevant tumors, there is still vast research potential for POLD4 in cancer." (PMID 37762224, 2023). "By integrating computational analysis with experimental data, our goal is to provide valuable insights into the potential therapeutic targeting of POLD4 and the modulation of the immune microenvironment in cancers." (PMID 37762224, 2023). "The results demonstrated a robust link between increased POLD4 expression and adverse clinical outcomes in a diverse range of cancer types." (PMID 37762224, 2023). "However, the exploration of POLD4 in other cancer types and the in-depth mechanisms of its actions remain limited, and its complete function has yet to be fully clarified." (PMID 37762224, 2023). "We analyzed the correlation between POLD4 and immune-related genes across various cancer types." (PMID 37762224, 2023). "Secondly, the distinct expression patterns in different cancer types suggest that POLD4 may play a context-specific role in oncogenesis." (PMID 37762224, 2023). "The heatmap displays the correlation between the POLD4 gene and pathway scores in pan-cancer." (PMID 37762224, 2023). "These cumulative findings indicate POLD4’s multifaceted engagement in cancer development." (PMID 37762224, 2023). "Elevated POLD4 expression may serve as an indicator of disease progression or severity in specific cancer types, which could aid in patient stratification and treatment decisions." (PMID 37762224, 2023). "In the TCGA cohort, POLD4 displayed distinct expression patterns in various cancer types." (PMID 37762224, 2023). "Utilizing a combination of POLD4-targeted cancer immunotherapy methods may offer higher efficacy compared to relying solely on a single treatment approach." (PMID 37762224, 2023). "By utilizing ESTIMATE scores, we established positive correlations between POLD4 expression and the presence of stromal and immune cells in the TME across various types of cancer." (PMID 37762224, 2023).
cancer (continued). "Through the Gene Set Cancer Analysis (GSCA) project, we utilized CTRP data online to perform a correlation analysis between POLD4 and drug sensitivity." (PMID 37762224, 2023). "In our investigation of the correlation between POLD4 expression and TME scores across 33 cancer types, intriguing findings emerged." (PMID 37762224, 2023). "Upregulation of the metabolic genes (ALDH18A1, CAD, CHKA, POLD4, PSPH, and SQLE) and aberrant expression of cancer-related genes (ALCAM, ITGA6, DDIT3, MAP3K6, and PAK1) were found in mouse fed with high-fat-high-cholesterol similar to human NASH-HCCs." (PMID 31795276, 2019). "We demonstrated for the first time the aberrant expression of cancer-related genes (ALCAM, ITGA6, DDIT3, MAP3K6 and PAK1) and metabolism-related genes (ALDH18A1, CAD, CHKA, POLD4, PSPH, SQLE and CFD) in human NASH-HCCs." (PMID 30367044, 2018).
tumor (10 papers, 2020 to 2025). "Using function analysis, it was uncovered that POLD4 exhibited intricate associations with signaling pathways spanning multiple tumor types." (PMID 37762224, 2023). "By examining the ImmuCellAI database, we found that POLD4 expression generally correlates with tumor-associated macrophages (TAMs), which play a significant role in promoting tumor growth." (PMID 37762224, 2023). "The elevated expression of immunosuppressive genes in association with POLD4 implies that POLD4 might contribute to an immunosuppressive microenvironment within the tumor." (PMID 37762224, 2023). "These comprehensive findings strongly suggest a close association between POLD4 expression and immune infiltration within tumor cells, consequently influencing patient prognosis and serving as a potential therapeutic target for the development of immunosuppressive treatments." (PMID 37762224, 2023). "Tumor sphere formation assays and limiting dilution assays showed that POLD4 overexpression reversed the effects of UCHL3 on the sphere-forming ability and self-renewal capacity of MES GSCs." (PMID 38829550, 2024). "Using immunohistochemical staining, we expanded the analysis of UCHL3 and POLD4 protein expression in GBM clinical tumor tissues, and a substantially positive correlation was presented." (PMID 38829550, 2024). "The analysis involved correlating POLD4 expression data with corresponding IC50 values of various drugs in the tumor cells." (PMID 37762224, 2023). "Supplements 1a-k display the outcomes of expression analysis for POLD4 in various pairs of tumor and adjacent normal tissues derived only from the TCGA dataset." (PMID 37762224, 2023). "Initial histopathologic tumor grade was indirectly associated with TMEM173 (STING), DNA-repair (ATM, POLD4) and hypoxia related genes." (PMID 35158950, 2022). "POLD4 was reported to participate in DNA replication and repair to sustain tumor cell survival, and in our study, the transcriptomics analysis indicated that it led to poor prognosis of NSCLC patients, however, the proteomics analysis revealed that it was a protective factor in LUSC." (PMID 39949782, 2025). "Interestingly, NEIL1, RAD52, and POLD4 showed overexpression in the adjacent mucosa compared to tumor tissue." (PMID 41275076, 2025). "Finally, mice bearing xenografts derived from MES GSCs treated with joint UCHL3 depletion and IR displayed a lower rate of tumor formation and prolonged survival compared to those following IR treatment, and POLD4 overexpression inhibited this synergism." (PMID 38829550, 2024). "Interestingly, while we found POLD4 as significantly up-regulated (x = 1.90) in the malignant part of the tumor compared to the normal region, it was massively down-regulated in both BCPAP (x = −26.96) and 8505C (x = −39.64) cells." (PMID 38790250, 2024). "The correlation with chemokine receptors and chemokines suggests that POLD4 may play a role in shaping the chemotactic signals within the tumor microenvironment." (PMID 37762224, 2023). "Conversely, elevated POLD4 expression might also indicate increased cellular proliferation, potentially contributing to tumor growth and progression." (PMID 37762224, 2023). "Such a revelation indicates that heightened POLD4 expression might heighten cellular responsiveness to these drugs, implying a potential avenue for enhancing their therapeutic efficacy for tumor patients with elevated POLD4 levels." (PMID 37762224, 2023). "However, a notable inverse relationship was observed between the POLD4 expression and tumor purity." (PMID 37762224, 2023).
tumor (continued). "Among them, the expression of TIPRAP, WSCD1, TCP11L2, DPP4, CAB39 and PDPK1 were down-regulated, while PARP1, DEPDC1B, CKAP2, ORMDL2, MRPL44, POLD4 and TMEM187 were increased in tumor group." (PMID 39949782, 2025). "Given the differential abundance of POLD4 in the GSC subtype and overexpression of POLD4 induced by IR in MES GSCs, to probe the effect of POLD4 on the biological functions of GSCs, we first performed a tumor sphere formation assay, limiting dilution assay." (PMID 38829550, 2024). "Therefore, POLD4 may indirectly regulate tumor immunity by influencing DNA replication and repair." (PMID 37762224, 2023). "Previous studies found that miR-1293 inhibited the growth of tumor cells by simultaneously targeting BRD4, APEX1, RPA1, and POLD4 via inhibiting the DNA repair pathway." (PMID 36147635, 2022). "Additionally, in LUAD, TCP11L2 was the only protein decreased in the tumor samples, and in LUSC, CAB39, DEPDC1B, DPP4, PDPK1, and POLD4 were significantly down-regulated." (PMID 39949782, 2025). "Additionally, the results have demonstrated a favorable correlation between POLD4 expression and the majority of genes responsible for immune suppression, chemokine receptors, chemokines, and MHC genes across a diverse range of tumor types." (PMID 37762224, 2023).
POLD4 also shares sentences with these, for which no sentence is quoted: COVID-19 (1 paper); Fanconi anemia (1); HIV-1 infection (1); non-small cell lung carcinoma (1); osteosarcoma (1); psychiatric disorder (1).